DAGLA (diacylglycerol lipase alpha)
Diseases named in the same sentence as DAGLA in open-access papers (continued):
Sharing a sentence is not in itself a finding about the gene and the disease.
myocardial infarction (1 paper, 2024). Gross necrosis of the myocardium, as a result of interruption of the blood supply to the area, as in coronary thrombosis. "Elevated levels of 2-AG have been observed in plasma can cardiac tissue in myocardial infarction induced- mice, associated with increased DAGLA expression in infarcted hearts." (PMID 38596466, 2024).
neuroblastoma (1 paper, 2012). Neuroblastoma (NB) is the most common solid, extracranial childhood tumor. "Overexpression of DAGLα in mouse neuroblastoma cells results in 2-AG accumulation, whereas knockdown of DAGLα by RNA interference blunts 2-AG production and prevents group I mGluR-stimulated production of this eCB." (PMID 21418147, 2012).
pancolitis (1 paper, 2009). Ulcerative colitis that involves the entire colon. "Quantification of epithelial immunoreactivity showed an increase of CB2 receptor, DAGLα and MAGL expression, mainly in mild and moderate pancolitis patients." (PMID 19730730, 2009). "During quiescent pancolitis, CB1, CB2 and DAGLα expression dropped, while NAPE-PLD expression rose, mainly in patients treated with 5-ASA or 5-ASA+corticosteroids." (PMID 19730730, 2009).
psychosis (1 paper, 2024). "In agreement with this, in patients with psychosis, the protein expression of CB2 receptors was significantly downregulated along with the gene expression of DAGLα in PBMCs." (PMID 38339171, 2024).
varicocele (1 paper, 2018). A condition characterized by the dilated tortuous veins of the spermatic cord with a marked left-sided predominance. "Noteworthy, none of the other ECS elements investigated (i.e., NAPE-PLD, DAGLα, FAAH, MAGL, CB1, and CB2) was affected by varicocele induction." (PMID 30539009, 2018).
neurodevelopmental disorder (7 papers, 2012 to 2025). A behavioral and cognitive disorder with onset during the developmental period that involves impaired or aberrant development of intellectual, motor, or social functions. "Several gene association studies have linked mutations in DAGLα (in most cases arising de novo in the patients) to neurodevelopmental disorders." (PMID 40523777, 2025). "Indeed, human mutations in DAGLα are associated with neurodevelopmental disorders." (PMID 40523777, 2025).
neurological disorders (4 papers, 2017 to 2026). "Recently, mutations in DAGLA, the gene for DAGLα, within the CNS were identified and implicated in neurological disorders in humans." (PMID 34749819, 2021). "Elucidating the interaction mechanism between FAM20C and ADAR, SAFB and DAGLA holds crucial implications for understanding both the physiological roles of FAM20C in the nervous system and its pathological contributions to neurological disorders." (PMID 40511628, 2026). "Rare genetic variants in the core endocannabinoid system genes CNR1, CNR2, DAGLA, MGLL and FAAH were identified in molecular testing data from 6,032 patients with a broad spectrum of neurological disorders." (PMID 29145497, 2017).
tumor (3 papers, 2019 to 2024). "TMA clinical data revealed a statistically significant correlation between DAGLA levels and several clinicopathological features, such as sex, vascular invasion, tumour number and tumour differentiation." (PMID 37414748, 2023). "In conclusion, we identified the DAGLA/2-AG axis as a crucial driver of tumour proliferation and the EMT process, resulting in the rapid progression and multikinase inhibitor resistance of HCC." (PMID 37414748, 2023). "Here, we found that the upregulation of components of the DAGLA/2-AG axis in HCC samples is correlated with tumour stage and patient prognosis." (PMID 37414748, 2023). "Among the genes, tumor related DAGLA and CEACAM1 were proven essential for the acquisition of resistance and for the recovery of sensitivity." (PMID 31847101, 2019). "Therefore, we speculate that the DAGLA/2-AG axis functions as an important tumour activator to promote HCC cell proliferation, invasion and metastasis in vivo and in vitro." (PMID 37414748, 2023). "Diacylglycerol lipase α (DAGLA) induces tumor cells to produce free FAs, enhances YAP1 activity, and aggravates the malignant phenotype and tumor progression in HCC." (PMID 38550587, 2024). "Subsequently, subcutaneous tumour models were established in nude mice by using Hep3B and PLC/PRF/5 cells with different DAGLA levels in order to explore the effect of DAGLA expression and verteporfin (a YAP antagonist) on lenvatinib resistance." (PMID 37414748, 2023).
cancer (1 paper, 2023). A tumor composed of atypical neoplastic, often pleomorphic cells that invade other tissues. "As an important hydrolytic enzyme that yields 2-AG and free fatty acids, diacylglycerol lipase alpha (DAGLA) is involved in exacerbating malignant phenotypes and cancer progression, but the role of the DAGLA/2-AG axis in HCC progression remains unclear." (PMID 37414748, 2023).
DAGLA also shares sentences with these, for which no sentence is quoted: depression (2 papers); Photophobia (2); Ataxia (1); Cognitive impairment (1); deafness (1); Fever (1); hepatocellular carcinoma (1); Huntington disease (1); intestinal inflammation (1); liver cancer (1); memory impairment (1); metastatic melanoma (1); movement disorder (1); Nystagmus (1); oral cancer (1); oral squamous cell carcinomas (1); overnutrition (1); Pain (1); Parkinsonism (1); psychiatric disorder (1); Rett syndrome (1); schizophrenia (1); ulcerative colitis (1).